METTL3 (methyltransferase 3, N6-adenosine-methyltransferase complex catalytic subunit)
Diseases named in the same sentence as METTL3 in open-access papers (continued):
Sharing a sentence is not in itself a finding about the gene and the disease.
breast cancer (continued). "In breast cancer, METTL3, HBXIP (mammalian hepatitis B X-interacting protein) and let-7g miRNA form a positive feedback loop (HBXIP/let-7g/METTL3/HBXIP) to promote cell proliferation." (PMID 30062093, 2018). "Previous reports using breast cancer stem cells have shown that hypoxic activation of HIF led to decreased RNA methylation through HIF-mediated induction of the demethylase ALKBH5 and METTL3 suppressor ZNF217." (PMID 30131850, 2018). "Exposure of breast cancer cells to hypoxia also leads to the upregulation of ZNF217, a transcription factor known to interact with METTL3 and inhibit its function." (PMID 28533023, 2017). "Furthermore, the correlation analysis revealed a positive correlation between the expression of METTL3 and miR-338-3p transcript level (r = 0.65, P < 0.0001) in breast cancer tissues of DOX-treated orthotopic breast cancer mouse." (PMID 40915108, 2025). "While METTL3 and METTL14 have been often reported to be upregulated in breast cancer in previous studies, METTL14 was found to be downregulated in the SCAN-B cohort, a trend that is also prevalently observed in The Cancer Genome Atlas (TCGA) cohort when METTL14 is altered." (PMID 40918643, 2025). "Intriguingly, METTL3 depletion has also been found to activate the CDKN1A/EMT pathway and m6A-BAX/caspase-9/-3/-8 cascade, thereby promoting proliferation, migration, and drug resistance in hormone receptor-positive HER2-negative breast cancer (HR+HER2-BC)." (PMID 40406121, 2025). "METTL3 mediates resistance to other chemotherapeutic drugs, including platinum‐etoposide in Small Cell Lung Cancer (SCLC), doxorubicin, 5‐fluorouracil (5‐FU), and oxaliplatin in CRC, Idarubicin in AML, and docetaxel in breast cancer." (PMID 38545841, 2024). "As it functions in breast cancer, hepatitis B X-interacting protein (HBXIP) could positively regulate METTL3 levels in GC cells, where METTL3 could interact with the oncogene MYC to increase m6A deposition, promoting proliferation, invasion, and metastasis." (PMID 37965577, 2023). "METTL3 increases MALAT1 protein levels in an m6A modification-dependent manner, recruits E2F1 and activates downstream AGR2 transcription to enhance the resistance of breast cancer cells to doxorubicin." (PMID 37264402, 2023). "Mechanistically, METTL3 upregulated PD-L1 expression by facilitating its mRNA stability in an m6A-IGF2BP3-dependent manner, which may guide new directions for breast cancer immunotherapy." (PMID 36960074, 2023). "On the contrary, another study reported that not only METTL3 but also other members of the writer complex such as METTL14 and WTAP are downregulated in breast cancer, suggesting that lower levels of m6A may contribute to breast tumorigenesis." (PMID 36725888, 2023). "Similarly, METTL3 enhances immune escape by upregulating PDL1 expression and inhibiting the activation of antitumor T cells in breast cancer." (PMID 37996892, 2023). "We found that METTL3 depletion promoted exon inclusion of the alternative exons of GNAS, MATR3, POLDIP3 and promoted skipping of the alternative exons of COMMD4, MARK3 and the non-m6A modified transcripts FASTK and EXOC7 in both breast cancer cell lines." (PMID 36725888, 2023). "METTL3 was identified as the m6A writer, with YTHDF2 as the reader protein of LATS1 mRNA, which plays a positive role in promoting both tumorigenesis and glycolysis in breast cancer." (PMID 36609396, 2023). "We show that both ADAR1 and METTL3 are upregulated in breast cancer samples, and ADAR1 positively correlates with METTL3; ADAR1 edits METTL3 mRNA and changes its binding site to miR532-5p, leading to increased METTL3 protein, which further targets ARHGAP5, recognized by YTHDF1." (PMID 36077054, 2022). "The expression of MALAT1 was shown to be enhanced by METTL3 through recruitment of E2F transcription factor 1 (E2F1), resulting in transcription of anterior gradient 2 (AGR2), and subsequent adriamycin resistance in breast cancer." (PMID 35721510, 2022).
breast cancer (continued). "Moreover, METTL3 methylates KRT7-AS to enhance the mRNA stability of keratin 7 (KRT7) depending on IGF2BP1-modified m6A, promoting breast cancer lung metastasis." (PMID 35541906, 2022). "Interestingly, the METTL3/IGF2BP3 axis promotes tumor immune escape via m6A modification of PD-L1 mRNA and suppression of T cell activation in breast cancer." (PMID 35794625, 2022). "To investigate the biological roles of ADAR1/METTL3/ARHGAP5 in breast cancer cells, we silenced ARHGAP5 and overexpressed ADAR1-p150 or METTL3 proteins in the cell lines, and then performed CCK-8, colony formation and transwell assays to detect cell proliferation, migration and invasion." (PMID 36077054, 2022). "In a further study, METTL3 also promoted maturation of miRNA-221-3p in an m6A-dependent manner, which negatively regulated HIPK2, upregulated the target gene Che-1, and induced chemoresistance of breast cancer cells to doxorubicin." (PMID 35721510, 2022). "Collectively, these clinical sample data also verified that the expressions of METTL3 and IGF2BP3 were positively correlated with PD-L1 and indicated that PD-L1 could be a potential downstream target of the METTL3/IGF2BP3 axis in breast cancer." (PMID 35197058, 2022). "Other subunits of METTL3 complex, namely WTAP, RBM15, KIAA1429 (also known as Virilizer homolog or VIRMA), and METTL14, displayed moderate-to-strong staining intensities in both normal and breast cancer tissues." (PMID 36289222, 2022). "In addition, METTL3 activated HBXIP via m6A modification, which promoted cell proliferation in breast cancer as part of a positive feedback loop." (PMID 35721510, 2022). "Moreover, ADAR1 edits the nearby ORF stop codon of METTL3 mRNA, leading to its binding site changing to miR-532-5p and resulting in increased METTL3 protein, which further targets ARHGAP5 to promote breast cancer progression in a YTHDF1-dependent manner." (PMID 36077054, 2022). "In present study, we identified that METTL3 participates in the regulation of homologous recombination repair (HR), which further influences chemotherapeutic response in both MCF-7 and MDA-MB-231 breast cancer (BC) cells." (PMID 35502895, 2022). "Interestingly, however, the expressions of METTL3 and METTL14 were still higher in normal and luminal types of breast cancer." (PMID 34044876, 2021). "METTL3 subsequently increases HBXIP expression by increasing m6A modification, thereby creating a positive feedback loop consisting of HBXIP/miR-let-7g/METLL3/HBXIP that accelerates breast cancer cell proliferation." (PMID 34136491, 2021). "However, another study revealed that the expression of METTL3, together with METTL14 and WTAP, was significantly decreased in breast cancer." (PMID 33376192, 2021). "Several members of m6A writer complexes and readers exhibited 1% mutation frequency, while main methyltransferases (METTL3, METTL14) and demethylases (FTO, ALKHB5) did not mutate in breast cancer samples." (PMID 34804948, 2021). "It showed that miR-483-3p mimic only inhibited the luciferase activity of the Wt reporter (not Mut), suggesting that METTL3 was targeted by miR-483-3p in breast cancer cells." (PMID 33431790, 2021). "Furthermore, the deceased patients had relatively reduced expression of FTO, METTL3, and METTL14 in tumor tissues, and increased levels of YTHDF1 and YTHDF3 than the alive patients who were diagnosed with breast cancer at the same period." (PMID 34804948, 2021). "Intriguingly, METTL3 could upregulate HBXIP in an m6A-dependent manner, which forms a positive feedback loop of HBXIP/let-7 g/METTL3/HBXIP, and thereby accelerates breast cancer cell proliferation." (PMID 32443966, 2020). "This mutual regulation of METTL3 and HBXIP promotes breast cancer progression." (PMID 32194861, 2020).
breast cancer (continued). "In this study, we used a series of bioinformatic databases and tools to jointly analyze the expression of m6A methylation transferases (METTL3, METTL14, WTAP, RBM15, RBM15B and ZC3H13) and investigate the prognostic value of METTL14 and ZC3H13 in breast cancer." (PMID 33363011, 2020). "Finally, the relationship between METTL3 and COL3A1 in breast cancer was analyzed with Pearson correlation analysis." (PMID 32766145, 2020). "METTL3 then promotes the expression of HBXIP gene through m6A modification, forming a positive feedback loop of HBXIP/let-7g/METTL3/HBXIP, which leads to accelerated cell proliferation in breast cancer." (PMID 29587823, 2018). "Taken together, the elevated SDHD and METTL3 expression suggests a potential epigenetic mechanism-driven SDHD activation, highlighting its previously unreported role in breast cancer biology and revealing a distinct pattern of SDH dysregulation in the Bangladeshi breast cancer population." (PMID 41751859, 2026). "For breast cancer, the PIN1/METTL3 axis may offer an alternative therapeutic target." (PMID 40919129, 2025). "As an oncogene, METTL3 may introduce the methyl group into the mRNA of target genes such as MYC and BCL2, promoting its translation that leads to cell differentiation and proliferation and affects apoptosis in acute myeloid leukemia and breast cancer." (PMID 38966069, 2024). "In addition, METTL3 expression has been shown to significantly increase with tumor progression and positively correlate with peptidyl-prolyl cis-trans isomerase NIMA-interacting 1 (PIN1) expression in breast cancer tissues." (PMID 37391814, 2023). "Thus, METTL3 depletion accompanied broader modulations in the AS landscape of breast cancer cells lines compared to the non-tumorigenic MCF10-A, suggesting a critical role of METTL3 in regulating tumor-associated AS switches." (PMID 36725888, 2023). "To determine whether m6A regulates AS in breast cancer, we first assessed the expression of METTL3 across non-tumorigenic and breast cancer cell lines." (PMID 36725888, 2023). "LDH release assay showed that METTL3-, IGF2BP3-knockdown and atezolizumab (anti-PD-L1) treatment increased the breast cancer cell sensitivity towards T-cell killing as compared to control groups, and these effects could be reversed by the overexpression of PD-L1." (PMID 35197058, 2022). "The expression level of METTL3 is not consistent in each subtype of breast cancer." (PMID 35721510, 2022). "Additionally, PD-L1-positive tissues expressed higher levels of METTL3 and PD-L1-negative tissues showed a concomitant decrease in IGF2BP3 expression, which suggested the existence of a METTL3-IGF2BP3-PD-L1 regulating axis in breast cancer." (PMID 35197058, 2022). "To determine whether ADAR1 overexpression enhances ARHGAP5 expression through METTL3, we knocked down METTL3 and overexpressed ADAR1-p150 protein and knocked down ADAR1 and overexpressed METTL3 in breast cancer cell lines to detect ARHGAP5 expression level by qRT-PCR." (PMID 36077054, 2022). "METTL3 expression is increased in gastric cancer tissues, hepaticcellcarcinoma (HCC), breast cancer (BC) and mediates the proliferation, metastasis, and colony formation of cancer cells." (PMID 34630412, 2021). "To explore the function of circMETTL3 in breast cancer, we knocked down circMETTL3 expression with small interfering RNAs (siRNA) and found circMETTL3 expression was inhibited, without affecting the parental gene METTL3." (PMID 33867838, 2021). "Interestingly, METTL3 upregulated HBXIP in an m6A dependent manner, forming a positive feedback loop of HBXIP/let-7g/METTL3/HBXIP, and in turn, accelerating the proliferation and invasion of breast cancer cells." (PMID 34108450, 2021). "Consequently, the findings pertaining to the role of the piR-31115/METTL3/YAP1/IGF2BP2 signalling pathway in tumour angiogenesis may not be directly applicable to all TNBC cases or other breast cancer types." (PMID 39820521, 2025).
breast cancer (continued). "Similarly, XBP1 has been shown to upregulate methyltransferase-like 3 (METTL3) and METTL4 to enrich m6a methylation and thus promote the mRNA stability of Calcium Binding And Coiled-Coil Domain 1 (CALCOCO1) and p62 (known ER-phagy regulators) in breast cancers." (PMID 41301006, 2025). "Taken together, the present study on METTL3/IGF2BP3-mediated N6-methyladenosine modification of PD-L1 mRNA and antitumor immunity provided a novel mechanism for m6A regulator-induced immunosuppression in breast cancer, which may have potential application as a novel therapeutic target." (PMID 35197058, 2022). "METTL3 depletion also contributes to tumour progression in Hormone Receptor Positive (HR+) and Human Epidermal Growth Factor Receptor 2 Negative (HER2‐) breast cancer." (PMID 38545841, 2024). "Although silencing of METTL3 did not dramatically affect the steady state mRNA levels, differences in gene expression (DEG) were more exacerbated in the breast cancer cell lines compared to MCF10-A cells." (PMID 36725888, 2023). "However, whether and how ADAR1 interacts with METTL3 in breast cancer has not been reported." (PMID 36077054, 2022). "The expression of METTL3, METTL14, RBM15B, and ZC3H13, but not of WTAP and RBM15, was significantly decreased in breast cancer." (PMID 33363011, 2020). "No increases in METTL3, METTL14 and WTAP protein levels were detected in VIRMA FL-transduced HS578T cells that already express high levels of endogenous full-length VIRMA or in breast cancer cells overexpressing VIRMA N-term compared to control cells." (PMID 37208522, 2023). "Furthermore, mining of TIMER database based on TCGA breast cancer samples demonstrated that only the mRNA expression levels of METTL14 and ZC3H13 were also lower in tumor samples, and there was not any difference of METTL3 and RBM15B." (PMID 33363011, 2020).
lung cancer (194 papers, 2018 to 2026). A malignant neoplasm involving the lung. "These demethylases regulate lung cancer progression and our study found that loss of METTL3 and FTO is linked to worse prognoses in LUAD." (PMID 40916616, 2025). "While m6A deposition in mRNAs occurs in the nucleus and elevated METTL3 levels are associated with survival of acute myeloid leukemia, non-catalytic functions of METTL3 outside the nucleus benefit lung cancer cells." (PMID 37609305, 2024). "A number of recent studies demonstrate that m6A modification is a key player in radioresistance in cancer cells. m6A modification due to METTL3 upregulation in non‐small cell lung cancer is implicated in resistance to carbon‐ion radiotherapy." (PMID 39661414, 2024). "Further GEO dataset (GSE30219 cohort, normal sample n = 14, tumor sample n = 293) analysis indicated that high METTL3 expression was associated with poor survival rate of patients with lung cancer." (PMID 37056933, 2023). "Another study published in Nature found that loss of METTL3 inhibits tumorigenicity and sensitizes lung cancer cells to BRD4 inhibition." (PMID 39872957, 2023). "For example, METTL3 has been reported to promote lung cancer‐associated transcript 3 expression by increasing its mRNA m6A level." (PMID 36564367, 2023). "In this review, we will focus on the underlying mechanism of METT3 in lung cancer and predict the future work and potential clinical application of targeting METTL3 for lung cancer therapy." (PMID 35331234, 2022). "EIF3H subunits have been proved to physically and functionally interact with METTL3, which causes the translation of many oncogenic mRNA, including bromodomain-containing protein 4 which is modified by m6A in primary lung cancer." (PMID 36051357, 2022). "More and more studies have demonstrated that METTL3 is strongly linked to the prognosis of lung cancer." (PMID 35331234, 2022). "Treatment of A549 and LC2/ad lung cancer cells with TGF-β caused upregulation of METTL3 and promoted epithelial to mesenchymal transition (EMT)." (PMID 36008936, 2022). "Recent studies have shown that aberrant m6A levels caused by METTL3 are involved in the malignant progression of various tumors, including lung cancer." (PMID 35331234, 2022). "For example, the m6A regulator gene METTL3 is overexpressed in lung cancer and associated with OS in patients with cancer." (PMID 36276113, 2022). "Recent findings have revealed that METTL3 is remarkably associated with different aspects of lung cancer progression, influencing the prognosis of patients." (PMID 35331234, 2022). "Loss of METTL3 attenuates TGF-β-induced morphological conversion of lung cancer cells, their cell migration potential, and EMT progression." (PMID 34616742, 2021). "High expression of METTL3 alleviated the suppression of lung cancer cell growth and migration caused by miR-338-5p." (PMID 34381710, 2021). "Methyltransferase-like 3 (METTL3)-induced m6A messenger RNA (mRNA) methylation has been documented to mediate drug resistance to cisplatin in nonsmall cell lung cancer, the underlying regulatory mechanism of which involves miR-1914-3p6." (PMID 33420414, 2021). "The relevance of m6A modification in lung cancer has been extensively studied, and several lines of evidence show that METTL3 is highly expressed in NSCLC cells and is associated with cell proliferation, invasion, and viability." (PMID 32404927, 2020). "For example, in lung cancer, METTL3 directly associates with translation machinery and enhances the translation of target mRNA (RGFR and TAZ) independent of its methyltransferase activity." (PMID 30031372, 2018). "Alteration of m6A methylation, due to the dysfunction of METTL3, has been also associated with the progression of human lung cancer and foremost with growth, survival and invasion of human lung cancer cells." (PMID 29958477, 2018).